TMEM221 (transmembrane protein 221)
Synonyms: Jiraiya
Tractability: Antibody: UniProt predicts a signal peptide or a membrane-spanning region.
Gene: Protein-coding gene on chromosome 19 (17,435,509 to 17,448,668, reverse strand). Ensembl gene ENSG00000188051.
Subcellular location: Membrane
Subcellular location (Human Protein Atlas): Nuclear membrane; Cytosol; Nucleoplasm
Gene Ontology:
Cellular component: membrane
Genetic constraint (gnomAD): Loss-of-function variants: 7 observed, 5.64 expected, observed/expected ratio (o/e) 1.24, 90% interval 0.69 to 1.88. That is too few expected variants to judge how well the gene tolerates losing a copy. Missense variants: 294 observed, 263.73 expected, observed/expected ratio (o/e) 1.11, 90% interval 1.01 to 1.23. Synonymous variants: 134 observed, 111.4 expected, observed/expected ratio (o/e) 1.2, 90% interval 1.04 to 1.39.
Homologues: Orthologues: chimpanzee TMEM221 (98% identical), macaque TMEM221 (96% identical), dog TMEM221 (87% identical), pig TMEM221 (84% identical), rat Tmem221 (73% identical), mouse Tmem221 (59% identical).